IL10 (interleukin 10)
Diseases named in the same sentence as IL10 in open-access papers (continued):
Sharing a sentence is not in itself a finding about the gene and the disease.
tumor (continued). "In this phase, the balance is skewed toward tumor progression resulting from the immunosuppressive molecules and cytokines, such as PD-L1, IDO, VEGF, TGF-β, and IL-10." (PMID 37345046, 2023). "IL‐10, IL‐12, and IL‐2 have recently been found to be important for DCs or effector CD8 T cell‐mediated anti‐tumor immunity." (PMID 36891351, 2023). "Accelerated local tumor irradiation decreased the frequency of Tregs, thus weakening the negative regulation on CD8+ T cells by the suppressive cytokines IL-10 and TGF-β, while conventional local tumor irradiation induced an increase in Treg levels." (PMID 37833255, 2023). "IL10 secretion by macrophages has been shown to downregulate the production of IL12 by DCs within the TME and blunt CD8+ T cell-mediated anti-tumor immune responses." (PMID 37830618, 2023). "The level of IL-1β, IL-6 and TNF-α were increased in tumor mice after DSF treatment, while the level of IL-4, IL-10 and TGF-β were increased after DSF treatment." (PMID 37305383, 2023). "In terms of the PSC function, CTHRC1 treatment markedly increased the genetic expression of tumor-promoting growth factors (EGF, HGF, and FGF by 4.9, 4.4, and 10.5 times, respectively) and cytokines (IL8 and IL10 by 3.7 and 2.9 times, respectively)." (PMID 37444482, 2023). "Cytokines, such as IL-2, IL-10, TGF-β and IFN, play a complex role in the regulation of immunity, which can promote or suppress anti-tumor immunity in different situations." (PMID 37398660, 2023). "The accumulation of TAMs following interactions with CAFs can exhaust the anti-tumor function of NK and CD8 + T cells by secreting TGF-β, COX-2, PGE2, IL-10, IL-4, IL-13, and some others." (PMID 37221555, 2023). "The levels of anti-tumor immune-response-related factors (interferon-γ (IFN-γ), interleukin-10 (IL-10), tumor necrosis factor- α (TNF-α) and IL-2) were evaluated in patients with negative and positive expressions of INHBA." (PMID 36984496, 2023). "Elevated levels of IL-10 in LILRB2+ breast cancer tissue positively correlates with advanced disease and lymph node metastasis, as well as reduction in tumour-infiltrating lymphocytes (TIL)." (PMID 38022598, 2023). "Among the cytokines tested, the most significant indicators of tumour progression in ALK + NSCLC were IL-6, IL-8 and IL-10." (PMID 37120670, 2023). "In the tumor microenvironment, IL-10-producing and IL-35-producing Tregs together drive Blimp1 expression and an exhausted phenotype in CD8+ tumor-infiltrating T cells." (PMID 38993904, 2023). "A2BR upregulation and activation signal macrophages towards the suppressive M2-like phenotype and secrete IL-10 and VEGF to promote angiogenesis and tumor growth." (PMID 38263981, 2023). "Tumour-biased monocytes upregulate c-FLIP, which in turn activates an immune suppressive program, partially by NF-κB activation, including IL-10, IDO-1, and PD-L1 expression." (PMID 36161514, 2023). "Accordingly, TGF-β1, IL-10 and CCL2 protein levels were significantly increased, and TNFα, IL-6, IL-1β and IL-12p40 protein levels were significantly decreased in tumor tissues in mice with MO-Mettl3 macrophages compared with mice with MO–nc macrophages." (PMID 37402945, 2023). "These cells and tumor cells drive the production of tumor facilitating cytokines such as TGF-β, IL-10, and IL-4, which also promote T-cell and CAR T-cell exhaustion." (PMID 36761757, 2023). "TAMEMs highly express mitogenic and angiogenic factors (e.g., VEGF, PDGF, and Ang) and immunosuppressive cytokines (e.g., IL‐10, CCL17, and TGF‐β), comparable to those in TAMs, which are typical features of the latter in promoting tumor development." (PMID 36541165, 2023). "The crosstalk between tumor cells and immune cells establishes this potent immunosuppressive milieu consisting of VEGF, TGF-β, IL-10, PGE2 soluble phosphotidylserines, soluble Fas or IDO." (PMID 37511431, 2023).
tumor (continued). "Recent studies have suggested that the M2-like TAMs enhance the production of IL-10, TGF-β, and PGE2, and consequently promote tumor angiogenesis." (PMID 36647777, 2023). "As the disease progresses, they exhibit a more M2 phenotype, secrete the anti‐inflammatory cytokine IL‐10, TGF, and promote tumor growth and invasion." (PMID 37937304, 2023). "Reciprocally, M2 macrophages can also produce cytokines such as IL10 and IL8, which promote tumor progression and the epithelial–mesenchymal transition." (PMID 37628994, 2023). "This is due to the increase in IFN-γ from CD8+ T cells, as also demonstrated in vivo in IL-10 transgenic mice with stimulated CD8+ T cells, resulting in the limited growth of immunogenic tumor cells." (PMID 37998326, 2023). "These regulatory B cells produce immunosuppressive cytokines, such as IL-10, which can suppress the activity of CD8+ T cells, ultimately promoting tumor progression." (PMID 37670933, 2023). "IL-27, which is secreted by tumor-infiltrating neutrophils, has been reported to drive CD39 expression in macrophages to maintain a suppressive phenotype and increase IL-10 secretion." (PMID 37313405, 2023). "In the present study, compared to those of pro-inflammatory cytokines, the levels of anti-inflammatory cytokines including IL-4, IL-10 and tumor growth factor-β (TGF-β) were suppressed in tumor-bearing mice after DSF treatment." (PMID 37305383, 2023). "TIM-3+Foxp3+ Treg cells express IL-10 and upregulate CTLA-4 and PD-1 expression, and these cells display more tumor suppressive function than TIM-3–Foxp3+ Treg cells." (PMID 36810098, 2023). "According to RT-qPCR analysis, the expression of the pro-tumor macrophage markers CD206, CD163, IL-6, IL-10, Arginase-1, and TGF-β were downregulated compared to the normal control group." (PMID 38098044, 2023). "Various immunosuppressive factors like TGF-β, IL-10, IDO, PGE2, and VEGF hamper the functions of DCs, hindering immune surveillance and promoting tumor advancement." (PMID 38008741, 2023). "In a phase I trial, the infusion of EGFRvIII-targeting CAR-T cells led to an adaptive immunosuppressive tumor response characterized by FOX3P+ Treg infiltration and the upregulation of immunosuppressive markers, including IDO-1, IL-10, PD-L1, and TGF-β." (PMID 36768342, 2023). "They secrete different immunosuppressive cytokines, including IL-10 and TGF-β, responsible for their immunosuppressive function to support tumor growth, proliferation, neoangiogenesis, and metastasis." (PMID 37275901, 2023). "MDSCs stimulate the production of Treg cells and increase the release of Immunosuppressive cytokines, such as interleukin-10 (IL-10), which specifically suppresses the activities of CD4 + and CD8 + T cells and promotes tumor growth." (PMID 37904131, 2023). "Most common reasons for inhibition of NK activity in the TME are hypoxia, low glucose concentrations, cytokines, tumor cell derives factors such as IL6, IL10, TGF-Beta, prostaglandin E2 (PGE2)." (PMID 37228595, 2023). "TAMs also regulate IL-10 and TGF-β production, induce immunosuppression, and promote tumor cell proliferation in the tumor microenvironment." (PMID 36900322, 2023). "Tregs also act as breaks on the immune system through immune checkpoint expression (CTLA-4 and PD-1), along with immunosuppressive cytokine (IL-10 and TGF-β) and metabolite (adenosine) secretion that affect a wide range of anti-tumor immune responses." (PMID 37108522, 2023). "Although iNKT cells can have immunosuppressive effects, e.g., the production of IL-10 by Treg-like NKT cells, iNKT cells show predominantly anti-tumorigenic functions in a variety of tumor models." (PMID 37511431, 2023).
tumor (continued). "In contrast, the IL-4, IL-10, IL-13, and transforming growth factor beta (TGF-β) present in the tumor microenvironment polarize macrophages into the M2 phenotype." (PMID 36986856, 2023). "Although antigen releasing and immune cell infiltration were higher in HEG, immune activation, tumor recognition and killing were lower in HEG, possibly due to a higher expression of IL-10 and ICP in HEG." (PMID 37465363, 2023). "Thus, we hypothesize that the anti-tumor role of cytotoxic Tr1 cells in this context is driven by the ability of PD1 blockade to preferentially enhance production of Th1 cytokines such as IFNγ over IL10 in Tr1-like CD4 T cells from human cancer samples." (PMID 37654482, 2023). "Data from preclinical experiments and a phase I study showed that GEN1046, another bsAb targeting 4-1BB and PD-L1, regresses tumor growth by increasing the proliferation of T cells and cytokine secretion, including IFN-γ, IL-10, and CXCL1072,73." (PMID 36971124, 2023). "Functionally, neoadjuvant chemotherapy induces proinflammatory cytokines and decreases pro-tumor cytokines from tumor-infiltrating T cells, with enhanced TNF-α and IL-2 and reduced IL-4 and IL-10 expression." (PMID 37173915, 2023). "The M2d subset is induced by IL-6 and M-CSF and secretes high IL-10 and low IL-12 and TGF-β cytokine production and CXCL10, CXCL16, and CCL5 chemokines to promote angiogenesis and tumor metastasis." (PMID 37020557, 2023). "They enhanced IL-10 production and differentiated into stem-like CAR-T cells, maintaining long-term anti-tumor responses." (PMID 37398660, 2023). "We measured circulating human cytokine levels in both tumor models and found that CAdVEC treatment induced expression of T helper 1 (TH1) [e.g., interferon-γ (IFN-γ)] and TH2 cytokines (e.g., IL-10), in addition to transgenic IL-12p70." (PMID 36989357, 2023). "Growing evidence shows that tumor cells can induce M2 polarization of TAMs through a variety of soluble factors, such as lactic acid, TGF-β, IL-10 and some exosomes." (PMID 37115489, 2023). "In combination, high expressions of IL-10 and TGF-β1 promotes the development of GI cancer, tumor metastasis, and leaded to worse prognosis." (PMID 37210494, 2023). "Cytokines, particularly IL10, that induce HHLA2 expression in monocytes fail to upregulate HHLA2 expression in tumor cell lines in vitro." (PMID 37891555, 2023). "Treg cells often abnormally accumulated in TME and expressed immunosuppressive molecules, including the cytokines IL-10, IL-35, and TGF-β, which suppressed the anti-tumor effects of T cells." (PMID 37355637, 2023). "M1 macrophages promote tumor destruction and produce TNF and interleukin-6, while M2 macrophages contribute to tumor progression by producing VEGF, MMP, and interleukin-10." (PMID 37280670, 2023). "Together this indicates that CD169+ Mo-M generated in a tumor microenvironment in vitro, act immunosuppressive in relation to NK and T cells via typical M2-like mediators (PGE2, ROS and IL10)." (PMID 37404831, 2023). "In contrast, M2 macrophages promote tumor development via proangiogenic factors and immunosuppressive cytokines like TGF-β and IL-10." (PMID 37925462, 2023). "IL‐10 induces the TAM M2 polarization that further secrete high IL‐10, IL‐6, TGF‐β, which can promoting fibrosis and enhance tumor growth." (PMID 36816959, 2023). "TAM-derived soluble molecules such as IL-10, IL-23, TGF-β, IDO, PGE2, and arginase 1 (ARG1) directly suppress the functions of tumor-infiltrating T and NK cells." (PMID 38008741, 2023). "In constant, M2 macrophages express the surface markers of CD163, CD86, and CD206 (MRC1, mannose receptor C-type 1), secrete cytokines including IL-10, TGF-β, and IL-6, and function in wound repair and tumor growth." (PMID 37749600, 2023). "They produce anti-inflammatory cytokines, including interleukin-10 (IL-10) and TGF-β, which play a role in promoting tumor cell survival, angiogenesis, and immunosuppression." (PMID 38022589, 2023).
tumor (continued). "Arnt−/− mice had more CD11b+Gr1+ neutrophil infiltration, fewer proinflammatory factor TNFα production, more anti-inflammatory factor IL-10 production and CXCR2 expression in neutrophils in tumor and draining lymph node (dLN) compared with WT control." (PMID 36859266, 2023). "Hence, both LOAd703 and LOAd732 induced a reversed IL-12/IL-10 ratio in the co-culture, which may be either due to changes induced by the tumor cells or because the DCs are activated to an even greater degree in co-culture and therefore secrete higher IL-10 in return." (PMID 37501121, 2023). "M2 macrophages produce antiinflammatory cytokines, including IL-10 and TGF-β, that promote tumor development." (PMID 37843274, 2023). "M2 TAMs are more dependent on high levels of oxidative phosphorylation, PPP is limited, and the main source of NADPH is reduced, which can produce IL-10 and vascular endothelial growth factor (VEGF) to promote tumor growth, angiogenesis, and metastasis 81-84." (PMID 37781517, 2023). "According to reports, tumor-related macrophages and M2 macrophages in HCC are regulated by interleukin 10, which accelerates the progression of HCC." (PMID 37165352, 2023). "IL-23 decreases infiltration of Treg and CD8+ T cells to promote the infiltration of M2-type macrophages and neutrophil cells and their overexpression and secretion of pro-tumor immunosuppressive cytokines, such as TGF-β and IL-10." (PMID 36835413, 2023). "The cancer cells secrete M2-type cytokines such as IL-10, VEGF, PDGF, CXCL12, CCL2, and CCL3 that mediate the recruitment of monocytes and M0 macrophages and drive them towards an M2 pro-tumor phenotype observed often in OC tissues." (PMID 38264664, 2023). "In tumor cells, activation of the MEK/ERK pathway increases the levels of serum interleukin-10 (IL-10) and transforming growth factor-β (TGF-β), which is key for Treg conversion." (PMID 37554401, 2023). "The cytokines IL-10, IL-17, and IFN-γ are the key mediators involved in suppressing the growth of tumor cells, IFN-γ, IL-10, and IL-17 production was increased in the spleen of LFA-1-deficient mice, suggesting that tumor immunity was unbalance or enhanced." (PMID 37723552, 2023). "The expression of immunosuppressive factors, such as IL-10 and TGF-β, as well as continuous stimulation of T cells by tumor antigens, results in impaired T cell function and, thus, ineffective clearance of cancer cells." (PMID 37511431, 2023). "qPCR results indicated that the effect of tumor-derived exosomes is very similar to that of IL-4, which efficiently increased the immunosuppressive factors, including TGF-β1 and IL-10." (PMID 36902024, 2023). "Bregs negatively regulate the immune response by producing anti-inflammatory factors such as IL-10, IL-35 and TGF-β, which has been confirmed in several related tumour studies." (PMID 36890557, 2023). "The role of cytokines in cancer, including OSCC, has been studied extensively and the main effector molecules regulating the pro-tumor immune activity are CSF-1, IL-6, VEGF, PGE-2, TGF-β and IL-10." (PMID 37568595, 2023). "IL-4 and IL-10 levels decreased more in the combination treatment than doxorubicin or PFPE alone, which correlated with reduced tumor progression." (PMID 37238871, 2023). "The stromal cells along with tumor cells release a host of immunosuppressive cytokines including TGF-β, IL-10, ARG-1, inducible nitric oxide synthase, COX2, PGE2, FAP, and PD-L1 to help the tumor evade CAR T cells." (PMID 37509394, 2023). "Meanwhile, activated TAMs can secrete various cytokines and chemicals, such as IL-10, TGF-β, and VEGF, which inhibit the function of immune cells, regulate immune responses, and promote tumor growth." (PMID 37744243, 2023). "Most Tumor-associated macrophages (TAMs) within a tumor release significant amounts of IL-10, which could indicate a correlative rather than a causal relationship between IL-10 and tumor growth." (PMID 36983741, 2023).
tumor (continued). "MHC class IIlow TAM increases the production of IL-10 and TGF-β to inhibit T cell proliferation and the secretion of MMP-9 and VEGF to promote tumor metastasis." (PMID 35163097, 2022). "NK cell proliferation and antitumor activity are inhibited by the secretion of various immunosuppressive factors by tumor cells, including prostaglandin E2, indoleamine 2,3-dioxygenase (IDO), IL-10, TGF-β and vascular endothelial growth factor (VEGF)." (PMID 36365103, 2022). "Tumor cells are known to produce several cytokines, such as TGF-β, VEGF, IL-6, and IL-10, which mediate the suppression of DC maturation and immune responses in the tumor microenvironment." (PMID 35584505, 2022). "The immunohistochemistry results revealed that the mice after WJR treatment had higher densities of IL-10, IFN-γ, and TNF-α than the NC group in the tumor tissue." (PMID 36212428, 2022). "In cancer, the co-expression of IL-10 and tumour antigens reprogram APC towards a tumour-tolerant phenotype." (PMID 36011012, 2022). "TAMs suppress the immune microenvironment by secreting chemokines and cytokines such as IL-10, TGF-β, and recruit Tregs to tumor sites to promote cancer development." (PMID 36313280, 2022). "In turn, LCs can produce substantial levels of IL-4, IL-10, IL-13, NAMPT, Arginase-2, and BMP-4, which regulate the pro-tumor functions of TAMs." (PMID 36532078, 2022). "MDSCs can also express IL-10 and TGF-β, which induce Treg differentiation and promote the suppressive tumor environment." (PMID 36389684, 2022). "A subset of IL-10-releasing HMOX1+ myeloid cells, spatially located around mesenchymal-like tumor cells, was identified to drive T cell exhaustion, and contribute to the immunosuppressive TME." (PMID 35920986, 2022). "IL-10 can inhibit the process of antigen presentation by downregulating the expression of MHC-II in APCs and MHC-I in tumor cells." (PMID 35784354, 2022). "The risk of tumorigenesis, the threshold concentration of TAA needed for stimulation, and the presence of immunosuppressive cytokines such as IL-10 and TGF-β that can offset proper anti-tumor response preclude the wide use of tumor lysates for vaccination." (PMID 35482149, 2022). "Both IL-10 and IL-6 induce activation of STAT3, but IL-6 induces proliferation and the production of inflammatory cytokines that promote tumor growth and is also considered to be a strong driver of many chronic inflammatory diseases." (PMID 35433880, 2022). "Mechanism studies have discovered that MSCs reduced and increased the concentrations of tumor‐promoting factors such as IL‐1 and TNF‐α, and tumor suppressor IL‐10 respectively." (PMID 34981659, 2022). "Based on the summary of literature data, tumor growth facilitates the induction and recruitment of CD4+ regulatory T cells that secrete IL-10 and TGF-β and suppress effector CD8+ T cell responses." (PMID 36194602, 2022). "The expression levels of COL4A1 were positively correlated with the gene expression levels of these immunosuppressive cytokines in all four analyzed tumor types, LGG (IL10: cor." (PMID 35455650, 2022). "BZLF1 itself has been shown to play a prominent role in tumor progression through its capability to induce VEGF and IL10 secretion, supporting vascularization and suppressing T cell responses." (PMID 36560713, 2022). "Then 5 × 105 MFC tumour cells were implanted in C57BL/6 mice; mice were intratumourally injected with the miR‐192‐5p antagomir, antagomir NC, anti‐IL‐10." (PMID 35969010, 2022). "In a mouse model, galectin-1 was reported to promote IL-10 secretion by PSC and induce fibrotic tumor stroma formation." (PMID 36428567, 2022). "They stimulate tumor progression by promoting tumor cell invasion, migration (MMPs), production of anti-inflammatory cytokines (TGF-beta, IL-10) and angiogenic factors (VEGF, TNF-alpha, HIF-1)." (PMID 35804950, 2022).